LEP (leptin)
Diseases named in the same sentence as LEP in open-access papers (continued):
Sharing a sentence is not in itself a finding about the gene and the disease.
Obesity (continued). "Leptin also promotes the expression of inflammatory cytokines, resulting in persistent inflammation and the development of obesity-related inflammatory states in obese individuals." (PMID 33138134, 2020). "Studies also indicate that obesity and disturbances in leptin signaling markedly affect the expression of neuronal and glial proteins." (PMID 33013310, 2020). "In the obesity + diabetes group, leptin correlated with sICAM1 rho = 0.786, and sVCAM1 negatively with glycemia/insulin rho = −0.85." (PMID 32858998, 2020). "It was also shown that the administration of leptin to ob/ob mice reversed their obesity phenotype and led to the conclusion that the physiological role of leptin is to reduce body weight and food intake." (PMID 33322719, 2020). "Lately, several reports found an empirical connection between obesity (namely leptin or its receptors) with several types of cancer." (PMID 32573960, 2020). "Possible leptin resistance developed during obesity can be attributed to the decrease in transport of leptin across the blood-brain barrier as well as an increase in the inhibitor SOCS3 (typically associated with diet-induced obesity in mice)." (PMID 32742493, 2020). "Obesity caused by a high-fat diet (HFD) has also been related to the release of pro-inflammatory cytokines in the hypothalamus and hippocampus, leading to leptin and insulin insensitivity and cognitive impairment." (PMID 33322180, 2020). "Particularly, considering the anorectic activity of leptin, propolis has potential to attenuate feeding and subsequently prevent obesity." (PMID 32630697, 2020). "Low serum LEP levels are also related to the prevention of obesity-related liver tumorigenesis in obese mice models." (PMID 33369452, 2020). "An observational trial confirmed that people with obesity have higher levels of leptin, adipsin, retinol binding protein-4 (RBP-4), IL-6, high sensitivity-C reactive protein (Hs-CRP) and lower levels of adiponectin and visfatin as compared to lean people." (PMID 33511131, 2020). "Because of its mode of action, leptin is thought to play some role in the development of obesity and insulin resistance." (PMID 33489589, 2020). "Elafin, via immune-derived miRNAs and cytokine, activates leptin sensitivity and expression that subsequently inhibit food consumption, obesity, hyperglycemia, and liver steatosis in HFD-treated male mice." (PMID 32733043, 2020). "Leptin is a cytokine-like hormone that primarily regulates appetite, is increased with obesity, and significantly higher expressed in obese women than in obese men." (PMID 32374776, 2020). "Much of the research on leptin performed during the early days focused on its role in regulating energy homeostasis and obesity at the level of the central nervous system." (PMID 31717265, 2019). "We suggest that the reduced calorie intake and serum leptin levels with spilanthol produced the anti-obesity effects by promoting energy consumption by increasing the affinity of leptin for its receptor." (PMID 31052312, 2019). "Another Lactobacillus gasseri strain, BNR17 with promising anti-obesity effects reduced body weight, white adipose tissue weight, serum leptin, and insulin levels in mice fed a high carbohydrate diet when administered twice daily for 12 weeks." (PMID 30678355, 2019). "The proinflammatory adipokine leptin regulates body weight and metabolism, exerting pleiotropic effects in many physiological systems including the liver, thereby linking obesity, insulin resistance, type 2 diabetes, and NAFLD." (PMID 30818874, 2019). "Rats fed a HFHS diet developed metabolic dysregulation and obesity with elevated plasma leptin and HbA1C concentrations." (PMID 31311115, 2019). "Food intake and metabolism are regulated by different hormones, such as leptin, whose circulating levels must be regulated very precisely and are often altered in obesity." (PMID 31717265, 2019).
Obesity (continued). "These SNPs were in/near the following genes: LEP, SLC32A1 (solute carrier family 32 member 1), GCKR (glucokinase regulatory protein), CCNL1 (cyclin-L1), and FTO (fat mass and obesity-associated)." (PMID 31766143, 2019). "Rare cases of loss-of-functions mutations affecting leptin and its receptor, as well as polymorphisms concerning ghrelin and its receptor, have been documented in human obesity, apparently validating the relevance of leptin and ghrelin for human physiology." (PMID 31656948, 2019). "Because the infertility of Lepob/ob mice cannot be restored by body weight reduction induced by food restriction, the leptin-signaling defect itself is considered responsible for the particular phenotype independent from the consequent obesity." (PMID 31509948, 2019). "Overall, in most individuals with obesity, leptin’s action to suppress appetite and increase energy expenditure seems to “saturate” well before the high levels observed in their blood." (PMID 30357355, 2019). "The findings of some studies indicate that T3 modulates the gene expression, serum levels of leptin, resistin, and adiponectin in obesity." (PMID 31666810, 2019). "Leptin is the key adipokine with mediator role on the adipose tissue-brain signaling pathways involved in obesity etiology, pathophysiology and health outcomes." (PMID 30605486, 2019). "On the other hand, the cross-talking of leptin and LFA with IFN signaling provides another rationale to associate IFNs with obesity." (PMID 31726661, 2019). "On the other hand, Leptin as an anti-obesity adipocytokine plays critical roles in regulating food intake, maintaining energy expenditure and body weight." (PMID 31341853, 2019). "As L44 mice developed obesity and diabetes despite high levels of amylin, insulin and leptin, they can be described as resistant to these hormones." (PMID 31601900, 2019). "The Nrf2 activity then suppressed the hypothalamic oxidative stress, subsequently improving the resistance of insulin and leptin related to obesity." (PMID 31817423, 2019). "One of the most significant adipokines is leptin, which has an influence on chronic inflammation and the development of osteoarthritis due to obesity." (PMID 31311115, 2019). "Metabolic parameters in serum samples, including lipidogram, glucose, leptin, ghrelin and insulin and obesity markers (BMI, W/H ratio, HOMA) were assayed and compared with values from 130 healthy female volunteers (controls)." (PMID 30635060, 2019). "Leptin levels are associated with BMI24, and obesity has frequently been associated with changes in the composition of the gut microbiome." (PMID 31882682, 2019). "Mice with SOCS3 deletion either in the whole brain or in proopiomelanocortin (POMC) neurons (the key leptin target neurons in the arcuate nucleus of the hypothalamus) are resistant to high-fat diet-induced obesity." (PMID 31141984, 2019). "The parameters for physiological and metabolic changes such as obesity, hypertension, hyperglycaemia, dyslipidaemia, and inflammatory biomarkers (NFκβ p65, TNFα, leptin and adiponectin) were measured." (PMID 31462242, 2019). "Altogether, an accumulating amount of data suggest that leptin is a potent indirect regulator of miRNA expression in tissues critically affected by obesity and during carcinogenesis." (PMID 31408957, 2019). "The positive correlations between leptin levels and anthropometric and metabolic parameters in children with obesity and the MS are well known." (PMID 31404407, 2019). "Deletion of SRC-1 in Pomc neurons in mice attenuates their depolarization by leptin, decreases Pomc expression and increases food intake leading to high-fat diet-induced obesity." (PMID 30979869, 2019). "In spite of the widely described effects of leptin on decreasing food intake and body weight on different animal models, the use of leptin as a therapeutic agent in an obesity driven context remains inefficient." (PMID 30935076, 2019).
Obesity (continued). "Normally, leptin is considered as an important hormone in reducing obesity, but extensive studies have revealed that obese individuals have a higher leptin level, and this is shown as a result of ‘leptin resistance’." (PMID 30763324, 2019). "Leptin is one of the many key-contributors to the development of cardiovascular disease, notably in the context of obesity and leptin levels can predict myocardial infarction." (PMID 30758470, 2019). "Leptin is in a direct relation with obesity and insulin resistance while adiponectin level is in an inverse correlation." (PMID 32082253, 2019). "Alterations in leptin signaling have deleterious effects in cardiac remodeling in pre-clinical models of obesity." (PMID 31428620, 2019). "Leptin resistance has also been proposed as a potential interface of inflammation and metabolic disturbance linking obesity and CVD." (PMID 31832026, 2019). "The changes induced by obesity and exercise were tissue‐specific and related to alterations in tissue lipid, protein and glycogen content and plasma insulin, leptin and triglyceride concentrations." (PMID 31466137, 2019). "Given that insulin resistance happens in obesity, the role of leptin in obesity etiology and pathophysiology is worth to discuss." (PMID 31191220, 2019). "The pro-inflammatory signaling molecules generated by adipocytes in obesity like IL-6 and leptin reach high systemic levels and trigger insulin resistance, developing type 2 diabetes and other complications." (PMID 30605486, 2019). "The CXCL12 rs501120 C allele and the FTO rs9939609 A allele were risk factors (rs501120: OR = 1.96, p = 0.02; rs9939609: OR = 2.2, p = 0.04), while LEP rs7799039 was a protective factor (rs7799039: OR = 0.6, p = 0.03) in the obesity group." (PMID 30764545, 2019). "We found that the obesity-prone FX animals had increased caloric intake, were lengthier and heavier, and had increased leptin levels, yet had significantly lower food intake ratio, suggesting that they had greater ability to store energy." (PMID 30664741, 2019). "It should be noted that a decrease in the intrahypothalamic leptin level in the agouti-mice was shown by us earlier, while a decrease in the intrahypothalamic insulin level in the melanocortin obesity was shown by us for the first time." (PMID 30870482, 2019). "Among these, leptin and ghrelin are known to be keystones of energy balance, to the extent that they can be considered targets for treating obesity." (PMID 31619003, 2019). "The genomic windows related to the slope for both traits also contain two growth-related genes, MC4R and LEP, both of which can regulate obesity and energy expenditure." (PMID 30760882, 2019). "These include activation of neurological pathways (associated with neuroinflammation, Huntington’s disease, and axonal guidance), cardiac hypertrophy, and metabolic pathways (for example, insulin receptor signalling and leptin signalling in obesity)." (PMID 31142858, 2019). "This should help putting together the big picture of how obesity afflicts the cardiovascular system by excluding a direct effect of leptin in this process." (PMID 31019683, 2019). "The hypothalamic IKKβ/NF-κB signaling pathway is involved in the inflammatory response, and contributes to the pathogenesis of obesity by inducing an insulin and leptin resistance through inflammation of the hypothalamic cells." (PMID 30886629, 2019). "Celastrol is a leptin-sensitizing agent with profound anti-obesity effects in diet-induced obese (DIO) mice." (PMID 31488870, 2019). "Breast milk leptin programs the offspring to be more protected against obesity and other metabolic alterations later on life." (PMID 31661820, 2019). "The hormone, leptin, seems to be involved in the pathophysiology of several diseases and metabolic states, including obesity and diabetes mellitus type 2." (PMID 30763324, 2019).
Obesity (continued). "The positive correlations between leptin levels and anthropometric and metabolic parameters in children with obesity and metabolic syndrome are well known." (PMID 31817641, 2019). "During the development of diet-induced obesity, the adipocyte mass expands to store the surplus calories and leptin secretion rises acting on peripheral tissues by stimulating compensatory fatty acid oxidation." (PMID 30717085, 2019). "Given this lack of correlation between ANGPTL5 levels and both leptin and adiponectin, we suggest that the role of ANGPTL5 in obesity and T2D occurs independently of leptin and adiponectin." (PMID 31396158, 2019). "Adiponectin and leptin can act as linkers between obesity and insulin resistance by performing special roles in the regulation of body metabolism." (PMID 31205951, 2019). "Among these genes, the LEP gene is considered as one of the major genetic factors involved in the obesity pathogenesis." (PMID 31871931, 2019). "This was the first randomized clinical trial to compare the effects of drinking yerba mate and green tea on serum levels of PON-1 and leptin in individuals affected by overweight or obesity and dyslipidemia." (PMID 30660196, 2019). "The importance of this pathway is underlined by the fact that blocking or inhibiting diet-induced hypothalamic inflammation prevents leptin insensitivity, glucose intolerance and obesity." (PMID 31168311, 2019). "Leptin is known to be higher in obese subjects and obesity can promote dysregulation of leptin signalling leading to central leptin resistance." (PMID 30621263, 2019). "This is consistent with other previous reports that increased gliosis in the ARCN is related to the enhanced leptin signaling in obesity." (PMID 31803004, 2019). "After the discovery of leptin, many studies evaluated the relationships between leptin and biological mechanisms related to obesity." (PMID 31238989, 2019). "This has been explained by a physiological mechanism of resistance to the catabolic effects of the Leptin action on obesity." (PMID 31871931, 2019). "When food environment is carefully controlled, sleep deprivation is associated with a lower secretion of the satiety hormone leptin and a higher secretion of hunger-stimulating hormone ghrelin, which may induce hunger feelings, and therefore, increase food intake and contribute to increased obesity." (PMID 31652950, 2019). "Serum leptin concentrations also correlated with body fat percentage in RA patients, working as an obesity marker." (PMID 31443349, 2019). "Leptin is thought to be a link between obesity and obesity-related complications including metabolic syndrome, type 2 diabetes, and cancer." (PMID 31292496, 2019). "Studies have shown a significant relationship between high levels of leptin and the inflammatory state present in obesity." (PMID 31146419, 2019). "Contributions of IKK-β in hypothalamic neurons and microglia to promoting leptin resistance and obesity are now clear." (PMID 31225498, 2019). "High leptin and low adiponectin are indicative of increased adiposity and suggests a potential parallel with human obesity and cardiovascular disease in males." (PMID 31242268, 2019). "A study using rats selectively bred to develop diet-induced obesity showed that rearing pups in large litters vs. normal litters (16 vs. 10 pups/dam) resulted in an attenuation of diet-induced obesity with attendant changes in leptin signaling." (PMID 30778334, 2019). "The results identified a series of obesity-related lncRNAs, among which the most crucial was lnc-leptin, transcribed from the promoter of leptin." (PMID 31109074, 2019). "The adipocyte-derived factor leptin has been recognized as an important molecular mediator of obesity in breast cancer." (PMID 31336913, 2019). "Leptin resistance in obesity is a well-established feature which extends beyond the regulation of NK cells and into the classical actions of leptin in energy homeostasis." (PMID 31018563, 2019).
Obesity (continued). "Recent reports showed that obesity should play a major role in the pathogenesis of PCOS through the insulin, leptin and endocannabinoid receptor, and by an association between insulin receptor polymorphism and PCOS was observed." (PMID 30635060, 2019). "The sensitivity to leptin's anorexigenic effects on chow diet was previously shown to predict the development of diet‐induced obesity." (PMID 31342663, 2019). "Such a lack of compatibility among the expression level, binding of epigenetic enzymes, and histone modifications only underlies the complexity of the mechanisms regulating the expression of leptin in obesity." (PMID 31408957, 2019). "Low grade inflammatory response to obesity is mainly maintain by adipocytes and immune cells secreting a variety of pro-inflammatory signals like interleukin-6, adipokines, leptin, resistin, TNF-α, monocyte chemoattractant protein-1 (MCP-1)." (PMID 30605486, 2019). "We have previously shown in this model of obesity that DIO + control treated rats had increased circulating plasma leptin concentrations compared to chow-fed control rats." (PMID 30707678, 2019). "The preexisting sensitivity to the anorexigenic effects of leptin, a predictor for obesity, correlates with the sensitivity to the thermoregulatory effects of leptin, which appears to be exerted, at least in part, at the level of the DMH." (PMID 31342663, 2019). "Obesity is a state of excess adipose tissue where elevated leptin levels fail to reduce appetite and increase energy expenditure." (PMID 30915034, 2019). "Using discriminant function analysis, it was possible to identify a combination of FSH and leptin as an independent predictor of obesity in pre-and postmenopausal women." (PMID 31509577, 2019). "Continuing future efforts in delineating downstream leptin signaling mechanisms regulating KATP channel trafficking in β-cells may offer novel therapeutic targets for improving glycemic control in type 2 diabetes patients by bypassing the leptin-resistance caused by obesity." (PMID 31151172, 2019). "Nutrient excess, a major driver of obesity, diminishes hypothalamic responses to exogenously administered leptin, a critical hormone of energy balance." (PMID 31403469, 2019). "Leptin, a hormone that induces satiety and increased energy expenditure was shown to be paradoxically increased in obesity, leading to the use of the concept of leptin resistance." (PMID 30787925, 2019). "With POMC‐mediated leptin and insulin function playing a major role in the pathological development of obesity and MeS, the methylation status of POMC thus represents a pivotal therapeutic target." (PMID 31660128, 2019). "Chronic leptin administration also improves hepatic glycerol metabolism, an important metabolite for de novo TG synthesis in hepatocytes, by restoring the coordinated regulation of fat-specific aquaporin-7 and liver-specific aquaporin-9, a step that might prevent obesity-associated hepatosteatosis." (PMID 31500090, 2019). "This narrow dose-response pattern, at least in most humans, has major implications for leptin physiology and obesity." (PMID 30357355, 2019). "Recent reports show that LGR4 homozygous mutant (LGR4m/m) mice display reduced adiposity and are resistant to diet- or leptin-induced obesity." (PMID 30344016, 2019). "Whereas endothelial leptin signaling is considered to be protective against neointima formation in the healthy state, obesity-induced leptin resistance can reverse this balance toward an atherogenic phenotype." (PMID 31694146, 2019). "Controversially, obesity does not necessarily influence the likelihood of developing RA; the evidential link is more definite for OA, where leptin appears to be a metabolic link between obesity and OA." (PMID 30917508, 2019). "Nonetheless, in obesity the hypothalamus becomes insensitive to leptin and insulin signifying dysregulation of hypothalamic energy balance." (PMID 31168311, 2019).